LYN (LYN proto-oncogene, Src family tyrosine kinase)
Description:
Non-receptor tyrosine-protein kinase that transmits signals from cell surface receptors and plays an important role in the regulation of innate and adaptive immune responses, hematopoiesis, responses to growth factors and cytokines, integrin signaling, but also responses to DNA damage and genotoxic agents. Functions primarily as negative regulator, but can also function as activator, depending on the context. Required for the initiation of the B-cell response, but also for its down-regulation and termination. Plays an important role in the regulation of B-cell differentiation, proliferation, survival and apoptosis, and is important for immune self-tolerance. Acts downstream of several immune receptors, including the B-cell receptor, CD79A, CD79B, CD5, CD19, CD22, FCER1, FCGR2, FCGR1A, TLR2 and TLR4. Plays a role in the inflammatory response to bacterial lipopolysaccharide. Mediates the responses to cytokines and growth factors in hematopoietic progenitors, platelets, erythrocytes, and in mature myeloid cells, such as dendritic cells, neutrophils and eosinophils. Acts downstream of EPOR, KIT, MPL, the chemokine receptor CXCR4, as well as the receptors for IL3, IL5 and CSF2. Plays an important role in integrin signaling. Regulates cell proliferation, survival, differentiation, migration, adhesion, degranulation, and cytokine release. Involved in the regulation of endothelial activation, neutrophil adhesion and transendothelial migration. Down-regulates signaling pathways by phosphorylation of immunoreceptor tyrosine-based inhibitory motifs (ITIM), that then serve as binding sites for phosphatases, such as PTPN6/SHP-1, PTPN11/SHP-2 and INPP5D/SHIP-1, that modulate signaling by dephosphorylation of kinases and their substrates. Phosphorylates LIME1 in response to CD22 activation. Phosphorylates BTK, CBL, CD5, CD19, CD72, CD79A, CD79B, CSF2RB, DOK1, HCLS1, LILRB3/PIR-B, MS4A2/FCER1B, SYK and TEC. Promotes phosphorylation of SIRPA, PTPN6/SHP-1, PTPN11/SHP-2 and INPP5D/SHIP-1. Mediates phosphorylation of the BCR-ABL fusion protein. Required for rapid phosphorylation of FER in response to FCER1 activation. Mediates KIT phosphorylation. Acts as an effector of EPOR (erythropoietin receptor) in controlling KIT expression and may play a role in erythroid differentiation during the switch between proliferation and maturation. Depending on the context, activates or inhibits several signaling cascades. Regulates phosphatidylinositol 3-kinase activity and AKT1 activation. Regulates activation of the MAP kinase signaling cascade, including activation of MAP2K1/MEK1, MAPK1/ERK2, MAPK3/ERK1, MAPK8/JNK1 and MAPK9/JNK2. Mediates activation of STAT5A and/or STAT5B. Phosphorylates LPXN on 'Tyr-72'. Kinase activity facilitates TLR4-TLR6 heterodimerization and signal initiation. Phosphorylates SCIMP on 'Tyr-107'; this enhances binding of SCIMP to TLR4, promoting the phosphorylation of TLR4, and a selective cytokine response to lipopolysaccharide in macrophages (By similarity). Phosphorylates CLNK (By similarity). Phosphorylates BCAR1/CAS and NEDD9/HEF1.
Synonyms: JTK8; SAIDV; p53Lyn; p56Lyn
Tractability: Small molecule: an approved drug acts on it; a structure with a bound ligand is known; a high-quality ligand is known; it has a high-quality binding pocket; it belongs to a druggable protein family. Antibody: its Gene Ontology location is reachable by antibodies, with high confidence; UniProt places it where antibodies can reach, with medium confidence; the Human Protein Atlas places it where antibodies can reach. PROTAC: it is named in the literature on targeted protein degradation; UniProt records ubiquitination sites on it; ubiquitination databases record sites on it; its protein half-life has been measured; a small molecule that binds it is known.
Target class: Kinase; TK protein kinase group; Enzyme; Protein Kinase; Tyrosine protein kinase Src family
Chemical probes: BAFETINIB, DGY-06-116 (high quality), Lyn-IN-1, SU6656
Gene: Protein-coding gene on chromosome 8 (55,879,825 to 56,014,169, forward strand). Ensembl gene ENSG00000254087.
Subcellular location: Cell membrane; Nucleus; Cytoplasm; Cytoplasm, perinuclear region; Golgi apparatus; Membrane
Subcellular location (Human Protein Atlas): Plasma membrane; Golgi apparatus; Vesicles
Pathways (Reactome):
Immune System: Antigen activates B Cell Receptor (BCR) leading to generation of second messengers; CD209 (DC-SIGN) signaling; CD22 mediated BCR regulation; Co-inhibition by CTLA4; Co-stimulation by CD28; Dectin-2 family; FCERI mediated Ca+2 mobilization; FCERI mediated MAPK activation; FCERI mediated NF-kB activation; FCGR activation; Fc epsilon receptor (FCERI) signaling; Growth hormone receptor signaling; Inactivation of CSF3 (G-CSF) signaling; Regulation of signaling by CBL; Role of LAT2/NTAL/LAB on calcium mobilization; Signaling by CSF1 (M-CSF) in myeloid cells; Signaling by CSF3 (G-CSF)
Signal Transduction: Erythropoietin activates Phosphoinositide-3-kinase (PI3K); Erythropoietin activates Phospholipase C gamma (PLCG); Erythropoietin activates RAS; Erythropoietin activates STAT5; Regulation of KIT signaling; Signaling by Erythropoietin; Signaling by SCF-KIT
Developmental Biology: EPH-Ephrin signaling; EPH-ephrin mediated repulsion of cells; EPHA-mediated growth cone collapse; EPHB-mediated forward signaling
Disease: Assembly and Release of Dengue Virus Virions; FCGR3A-mediated IL10 synthesis; FCGR3A-mediated phagocytosis; Signaling by phosphorylated juxtamembrane, extracellular and kinase domain KIT mutants
Hemostasis: Cell surface interactions at the vascular wall; GPVI-mediated activation cascade; PECAM1 interactions; Platelet Adhesion to exposed collagen
Cell Cycle: Cyclin D associated events in G1
Gene Ontology:
Molecular function: ephrin receptor binding; non-membrane spanning protein tyrosine kinase activity; phosphorylation-dependent protein binding; protein binding; protein tyrosine kinase activity; scaffold protein binding; signaling receptor activator activity; transmembrane transporter binding; kinase activity; signaling receptor binding; ATP binding; enzyme binding; gamma-tubulin binding; glycosphingolipid binding; immunoglobulin receptor binding; integrin binding; phosphoprotein binding; platelet-derived growth factor receptor binding; protein kinase activity; protein-containing complex binding; ubiquitin protein ligase binding
Biological process: C-X-C chemokine receptor CXCR4 signaling pathway; cell surface receptor protein tyrosine kinase signaling pathway; cellular response to retinoic acid; DNA damage checkpoint signaling; DNA damage response; eosinophil differentiation; ephrin receptor signaling pathway; fatty acid transport; hematopoietic progenitor cell differentiation; inflammatory response; interleukin-5-mediated signaling pathway; negative regulation of B cell receptor signaling pathway; negative regulation of cell population proliferation; peptidyl-tyrosine phosphorylation; positive regulation of amyloid precursor protein catabolic process; positive regulation of MAPK cascade; positive regulation of mast cell proliferation; positive regulation of neuron projection development; positive regulation of toll-like receptor 4 signaling pathway; positive regulation of toll-like receptor 9 signaling pathway; protein autophosphorylation; protein phosphorylation; regulation of cell adhesion mediated by integrin; regulation of monocyte chemotaxis; B cell homeostasis; and 58 more
Cellular component: cytoplasmic side of plasma membrane; cytosol; extracellular exosome; Golgi apparatus; membrane raft; nucleus; perinuclear region of cytoplasm; plasma membrane; cytoplasm; endocytic vesicle membrane; lysosomal membrane; adherens junction; glutamatergic synapse; integrin alpha2-beta1 complex; lysosome; membrane; mitochondrial crista; mitochondrial membrane; postsynaptic specialization, intracellular component
Genetic constraint (gnomAD): Loss-of-function variants: 9 observed, 55.66 expected, observed/expected ratio (o/e) 0.16, 90% interval 0.096 to 0.28. The upper end of that interval is the gene's LOEUF score, 0.28, which puts it in group 1 of 6, group 1 being the genes least tolerant of losing a copy. Missense variants: 327 observed, 593.72 expected, observed/expected ratio (o/e) 0.55, 90% interval 0.5 to 0.6. Synonymous variants: 199 observed, 213.81 expected, observed/expected ratio (o/e) 0.93, 90% interval 0.83 to 1.05.
Homologues: Orthologues: chimpanzee LYN (100% identical), dog LYN (97% identical), pig LYN (97% identical), guinea pig LYN (96% identical), mouse Lyn (96% identical), rat Lyn (96% identical), macaque LYN (92% identical), rabbit LYN (92% identical), tropical clawed frog lyn (84% identical), zebrafish lyn (75% identical). Paralogues in human: HCK (70% identical), LCK (63% identical), BLK (60% identical), FYN (58% identical), YES1 (56% identical), FGR (55% identical), SRC (54% identical), FRK (47% identical), ABL2 (38% identical), ABL1 (38% identical), SRMS (36% identical), PTK6 (35% identical), and 20 more.
Diseases named in the same sentence as LYN in open-access papers:
LYN is named in the same sentence as 130 diseases in open-access papers, as found by Europe PMC text mining. Sharing a sentence is not in itself a finding about the gene and the disease. The quoted sentences say what the papers report.
breast cancer (24 papers, 2011 to 2025). A primary or metastatic malignant neoplasm involving the breast. "LYN mRNA and protein caused cell proliferation, migration and invasion capability of breast cancer, chronic myelogenous leukemia, prostate cancer, colorectal cancer, oral cancer and gastric cancer." (PMID 30524205, 2018). "Lyn facilitates glioblastoma cell survival, and LYN expression is associated with migration and invasion in breast cancer." (PMID 27414409, 2016). "LYN encodes a tyrosine protein kinase of the Src family which is abundantly expressed in immune cells and involved in the occurrence and progression of tumors, including breast cancer, lung cancer, colorectal cancer and chronic leukemia." (PMID 35433689, 2022). "Use of two short hairpins targeting human LYN demonstrated that LYN knockdown in human breast cancer cells also significantly impaired cell growth in the BRCA1-mutated HCC1937 human breast cancer cell line and in cells from a BRCA1 mutant breast cancer patient-derived xenograft (PDX)." (PMID 30590041, 2018). "LYN is overexpressed in human triple-negative breast cancer (TNBC; the breast cancer subtype most strongly associated with BRCA1 loss) and is also expressed at high levels in mammary tumours from Brca1 conditional knockout mice." (PMID 38149669, 2024). "Here, we find contradictory evidence for the role of LYN in mammary tumours, potentially related to functions in multiple cell types within a tumour." (PMID 38149669, 2024). "Previous studies on the mammary epithelium and breast cancer, including our own, have highlighted LYN as a positive regulator of cell growth and survival." (PMID 38149669, 2024). "The multifaceted role of LYN indicates that it is likely to present difficulties as a therapeutic target in breast cancer." (PMID 38149669, 2024). "Overexpression of EPHA10, LYN, and PTK2 (BL1 subtype-specific TK genes) is linked to the severity of breast cancer and can be used as the biomarker for TNBC." (PMID 36672350, 2023). "About half of them in BL1 and BL2 were overlapping, such as LYN, JAK2, SYK, and EGFR, which were reported to be associated with the aggressiveness of breast cancer, particularly in TNBC." (PMID 36672350, 2023). "Immunohistochemical analysis of mammary tumors indicated that nuclear SphK1 can co-localize with Erk1/2, Lck/Yes novel tyrosine kinase (LYN), V-akt murine thymoma viral oncogene homolog (AKT), or Nuclear Factor κB (NF-κB)." (PMID 33919234, 2021). "There is some evidence that LYN is generally anti-apoptotic, and this warrants further investigation in breast cancer." (PMID 30590041, 2018). "show that in aggressive breast cancers, LYN activity is deregulated by a change in patterns of splice isoform expression." (PMID 30590041, 2018). "PIN1 knockdown significantly reduced LYN Y397 phosphorylation in a human BRCA2 mutant breast cancer cell line and in primary mouse Brca2 null tumor cells." (PMID 30590041, 2018). "Other mechanisms contributing to the underlying LYN dysregulation in TNBC remain to be defined, as does the potential wider role of LYN in breast cancer." (PMID 30590041, 2018). "The SRC-family kinase LYN is highly expressed in triple-negative/basal-like breast cancer (TNBC) and in the cell of origin of these tumors, c-KIT-positive luminal progenitors." (PMID 30590041, 2018). "We have previously demonstrated that Brca1 mutation-associated breast cancers originate from luminal ER− progenitors and that c-KIT and LYN are expressed in mouse Brca1 mammary tumors." (PMID 30590041, 2018). "In BRCA1-dysfunctional breast cancers, LYN activity is upregulated by a prolyl isomerase (PIN1) that is normally repressed by BRCA1." (PMID 30590041, 2018). "A recent study showed that inhibition of LYN resulted in synthetic lethality after dasatinib treatment in breast-cancer cell lines expressing high levels of MYC." (PMID 27756880, 2016).
breast cancer (continued). "We also found that LYN is a potential therapeutic target of dasatinib in clinically aggressive basal-like breast cancer." (PMID 27756880, 2016). "Our group previously reported that LYN is among the top epithelial-mesenchymal transition (EMT) signature genes in mesenchymal breast cancer cell lines, and high LYN expression is correlated with lower OS." (PMID 27756880, 2016). "LYN was suggested as a candidate marker of dasatinib sensitivity based on gene expression signatures from a panel of breast cancer cell lines." (PMID 27756880, 2016). "LYN has also been identified as an important driver of phospho-tyrosine signalling to induce invasiveness within basal subtype breast cancers, although that study reported a relatively low level of activated LYN within the MDA-MB-468 cell line." (PMID 25975820, 2015). "Together, these findings highlight that co-treatment of COR and LYN in the non-germline BRCA mutated breast cancer effectively reduced tumor volume." (PMID 40764992, 2025). "Downstream mediators linked to LYN activation of NFκB include MEK, IKKα (or CHUK), PI3K, MAPK and IκB, and there is also support for a role of NFκB activation in BRCA1 loss-of-function-associated breast cancers." (PMID 38149669, 2024). "Both LCK and LYN regulate migration and inhibition and LYN reduces breast cancer metastasis." (PMID 35150959, 2022). "Therefore, our findings demonstrate dual mechanisms, uncoupling from upstream signals and changing splice isoform ratios, driving the activity of LYN in aggressive breast cancers." (PMID 30590041, 2018). "Thus, dual mechanisms—uncoupling from upstream signals and splice isoform ratios—drive the activity of LYN in aggressive breast cancers." (PMID 30590041, 2018). "In addition, LYN overexpression has been reported in several cancers, such as chronic myelogenous leukemia, colorectal cancer, breast cancer, prostate cancer, oral cancer, renal cancer and gastric cancer." (PMID 27690342, 2016). "Moreover, LYN is expressed in some solid tumors and serves as a potential therapeutic target for colon, prostate, glioblastoma, and more aggressive subtypes of breast cancer." (PMID 26065685, 2015). "The cells of origin of BRCA1-associated mammary tumours, the mammary luminal epithelial estrogen receptor (ESR1)-negative stem/progenitor population, express the c-KIT (or KIT) receptor tyrosine kinase at high levels, as well as its downstream pathway member, the SRC-family kinase LYN." (PMID 38149669, 2024). "Similarly, while LYN was involved in the tumourigenesis of breast cancer, its expression was not linked to changes in patients survival." (PMID 29937990, 2018). "In addition, LYN overexpression has been reported in several cancers, such as chronic myelogenous leukemia, colorectal cancer, breast cancer, prostate cancer, oral cancer, renal cancer and Ewing’s sarcoma; nonetheless, no previous study has evaluated the role of LYN in gastric carcinogenesis." (PMID 26460485, 2015). "This indicates that LYN may play a role for ER+ breast cancer acquiring hormone-independent growth." (PMID 24883302, 2014). "To demonstrate a direct functional link between PIN1 expression and LYN activity, we knocked down PIN1 in primary mouse Brca1 null cells and cells from a BRCA1 mutant human breast cancer cell line and the BRCA1 mutant PDX." (PMID 30590041, 2018). "In TCGA data provided by the Cancer Genome Atlas, we find HCK, LYN, LCK, and CSK are higher in basal-like breast cancer subtypes." (PMID 28771473, 2017). "LYN, a major member of the SFK family, is expressed in many solid tumors, including colon cancer, prostate cancer, glioblastoma, and breast cancer, and plays a critical role in tumor progression." (PMID 27756880, 2016). "In contrast, the expression patterns of SNX, HTR2B, RGS4, and LYN were not homogeneous and differed among the breast cancer subtypes." (PMID 39267843, 2024).
breast cancer (continued). "LYN activity has been reported to promote the epithelial-mesenchymal transition through Vav-Rac1-PAK1-mediated control of SNAI protein localisation and stability in multiple cancer types, including breast cancer." (PMID 38149669, 2024). "Furthermore, we address the role of the two LYN splice isoforms in breast cancer and find that only full-length LYN (LYNA), as opposed to LYNΔ25–45 (LYNB), promotes cell migration and invasion." (PMID 30590041, 2018). "High level expression of LYN, a member of the SRC family of non-receptor tyrosine kinases, has been associated with epithelial/mesenchymal transition and invasion by breast cancer cells and with poor survival of breast cancer patients." (PMID 21364760, 2011). "Furthermore, the full-length LYN splice isoform (as opposed to the Δaa25–45 variant) drives migration and invasion of aggressive TNBC cells, while the ratio of splice variants is informative for breast cancer-specific survival across all breast cancers." (PMID 30590041, 2018). "We next asked whether the two LYN isoforms, LYNA and LYNB, play different roles in breast cancer biology, independent of the BRCA1-PIN1-LYN axis." (PMID 30590041, 2018).
lupus (18 papers, 2013 to 2024). "Prior studies have shown that upon B-cell activation, LYN mediates inhibitory signaling pathways by BCRs, whereas defects in LYN are associated with human lupus." (PMID 38129902, 2023). "In an in vitro study, the activation of TLR-triggered signaling in dendritic cells was observed after LYN deletion, leading to the spontaneous development of an autoimmune disease with features of human systemic lupus erythematosus." (PMID 36263434, 2022). "Lastly, we note that patients with lupus, an autoimmune disease characterized by B cell hyperactivity, show decreased protein levels of LYN and high rates of pregnancy complications." (PMID 35416936, 2022). "Common alleles of LYN, like BLK, have been implicated in SLE by GWAS13 and Lyn deficiency induces a lupus-like phenotype in mice." (PMID 31101814, 2019). "B cells from lupus patients are known to be hyperresponsive to stimulation through the BCR as evidenced by increased LYN and ERK1/2 phosphorylation." (PMID 23977035, 2013). "STING also plays a crucial role in systemic lupus erythematosus (SLE) in response to the recognition of self-DNA via LYN interaction and phosphorylation to induce conventional DC (cDC) maturation and plasmacytoid DC (pDC) differentiation." (PMID 33643304, 2020).